CLDN1 (claudin 1)
Diseases named in the same sentence as CLDN1 in open-access papers (continued):
Sharing a sentence is not in itself a finding about the gene and the disease.
colitis (continued). "A number of studies have reported an elevation in claudin-1 expression in both experimental colitis models and patients with IBD." (PMID 32630643, 2020). "We used qRT-PCR and Western blotting assays and demonstrated that SA reduced the activation of the NLRP3 inflammasome and attenuated intestinal permeability by enhancing the expression of ZO-1, occludin, and claudin-1 in colitis mice." (PMID 33312339, 2020). "Sinapic acid treatment also increased the protein levels of claudin-1, occludin, and ZO-1 in the colons of the colitis mice (p < 0.05)." (PMID 33312339, 2020). "Meanwhile, studies have also reported a decrease in claudin-1 expression in an experimental colitis model." (PMID 32630643, 2020). "In DSS-induced colitis mice, both the mRNA and protein levels of occludin, ZO-1, and claudin-1 were found to be decreased in the colon tissue." (PMID 33312339, 2020). "The expressions of tight junction (TJ) proteins occludin and claudin 1 were significantly increased by the taxifolin supplementation, indicating that the gut barrier was enhanced by taxifolin to suppress colitis." (PMID 33664740, 2020). "It was also observed that sinapic acid also enhanced the protein levels of occludin, ZO-1, and claudin-1 to maintain the normal function of the intestinal barrier in DSS-induced colitis in mice." (PMID 33312339, 2020). "On the basis of that observation, it is conceivable that PWS can improve paracellular permeability as well as epithelial barrier function in DSS + CD-induced colitis by upregulating occludin and claudin-1 expressions." (PMID 31888274, 2019). "The expressions of colonic claudin-1, claudin-3, claudin-5, claudin-7 and claudin-8 in colitis mice were markedly decreased as compared with control mice." (PMID 22073304, 2011). "The immunostaining of claudin-1 was decreased in intensity in colitis mice, and enhanced when treated with CXCR4 antagonist AMD3100." (PMID 22073304, 2011). "Treated with CXCR4 antagonist AMD3100 significantly promoted colonic claudin-1, claudin-3, claudin-5, claudin-7 and claudin-8 expressions, and also decreased colonic claudin-2 in colitis mice." (PMID 22073304, 2011). "This study found that both LWB and HWB could alleviate the reduced mRNA expression levels of tight junction proteins (ZO-1, Claudin-1, and Occludin) present in the colonic tissue of mice induced with colitis." (PMID 38254526, 2024). "Furthermore, Gpr81 knockout resulted in increased protein expression of MMP9 and decreased expressions of Claudin-1, ZO-1, and Occludin in the colitis mice." (PMID 38474712, 2024). "Occludin, Claudin-1 and ZO-1 are intestinal epithelial tight junction marker proteins, and ZO-1 and Occludin were considered as valuable predictive proteins for the severity of colitis and mucosal healing." (PMID 36766197, 2023). "It was shown to be active on alleviating DSS-induced colitis and increasing the expression of Claudin-1 and ZO-1 in the colon, which might be induced by enhancing the autophagy via blocking the activation of PI3K/Akt/mTOR signaling pathway." (PMID 37942490, 2023). "Similar to Gegen Qinlian decoction, Huangqin decoction could alleviate DSS-induced colitis and upregulate tight junction proteins, such as claudin-1 and ZO-1." (PMID 37942490, 2023). "Sesamol and apigenin could increase the expression of Occludin, claudin-1, and Zo-1 to attenuate colitis." (PMID 37887381, 2023). "Besides, ZO-1, Claudin-1, and Occludin have been classified as fundamental tight junction proteins and their repression elicited potential in the alleviation of colitis." (PMID 36890151, 2023). "In a colitis mouse model, SA was found to enhance the expression of ZO-1, occludin, and claudin-1." (PMID 37444374, 2023). "Additionally, the inosine intervention significantly elevated the expression of tight junction proteins (ZO-1, occudin, and claudin-1) in mice with colitis." (PMID 37762155, 2023).
colitis (continued). "CLDN-1 regulates colonic epithelial cell differentiation in a Notch and Akt-dependent manner and promotes colitis severity by regulating MMP-9 and p-ERK signaling, while impairing colitis-associated injury/repair." (PMID 35571126, 2022). "In DSS-induced colitis in mice, intestinal permeability increased significantly, and tight-junction proteins occludin, claudin 1 and claudin 3 that are closely related to intestinal permeability decreased, whereas RJ significantly improved the changes of intestinal permeability." (PMID 35631210, 2022). "Furthermore, corylin, at a dose of 100 mg/kg (H), significantly increased the levels of claudin-1 and occludin, which were even higher than for the effects produced by corylin at a dose of 25 mg/kg (L) compared with colitis mice." (PMID 35269806, 2022). "Repeated electroacupuncture could improve DSS-induced colitis, repair TJ damage (both claudin-1 and occludin) and inhibit proinflammatory mediators." (PMID 36101343, 2022). "In the present study, whether at the gene or protein level, treatment with BPIS upregulated the expression of Claudin-1, Occludin, and ZO-1 in colitis mice colons." (PMID 36479296, 2022). "We propose that the effects of corylin on DSS-induced colitis mice are related to the regulation of the colonic mucosal barrier function, where the expression levels of claudin-1, ZO-1, and occludin play important roles in maintaining the intestinal mucosal barrier function." (PMID 35269806, 2022). "It is noteworthy that claudin-1 was positively correlated with colitis severity in IBD patients." (PMID 33807544, 2021). "In contrast to KO mouse models, transgenic mouse models that overexpress specific claudins are limited, and only claudin-1-overexpressing transgenic mice with simultaneous adenomatous polyposis coli (APC) deletion or induced colitis have shown a role for claudin-1 in supporting tumorigenesis." (PMID 34354941, 2021). "Accordingly, CLDN1 expression was down-regulated in DSS-induced colitis." (PMID 33668818, 2021). "The decreased expression of tight junction proteins (ZO-1, OCLN, and CLDN1) in colon tissues of colitis mice challenged by TNBS was enhanced by YST treatment, indicating the defective colonic mucosal barrier could be restored by YST." (PMID 34055024, 2021). "In rats with TNBS-induced colitis, diet supplementation with grape peel powder rich in polyphenols and fiber or with fish oil rich in ω-3 PUFAs strongly upregulated the ZO-1, CLDN1, CLDN5 and CLDN8 protein expressions in colon." (PMID 33806347, 2021). "Notably, the expression of claudin-1 remained controversial in the present experimental colitis model." (PMID 32630643, 2020). "However, sinapic acid treatment was able to increase the mRNA expression of claudin-1, occludin, and ZO-1 in the colons of the colitis mice." (PMID 33312339, 2020). "Interestingly, treatment with ED amino acids markedly decreased epithelial architectural derangements and restored the expression of occludin, ZO-1, and claudin-1 protein levels in colitis mice." (PMID 32855978, 2020). "Further studies are needed to clarify the role of claudin-1 in the pathogenesis of colitis." (PMID 32630643, 2020). "Moreover, in the present study, we found that treated with CXCR4 antagonist AMD3100 significantly promoted colonic claudin-1, claudin-3, claudin-5, claudin-7 and claudin-8 expressions, and also decreased colonic claudin-2 in colitis mice." (PMID 22073304, 2011). "Interestingly, this pathogenic role of decreased PER2 in human IBD appears to contrast with findings in mouse models, where mice with a mutated Per2 gene showed increased expression of tight junction proteins (occludin and claudin-1) and decreased susceptibility to DSS-induced colitis." (PMID 40332348, 2025). "Additionally, in mice with DSS-induced colitis, syringic acid at doses of 25 and 50 mg/kg prevented colon damage, alleviated proptosis, and increased the mRNA expression of intestinal barrier proteins (claudin-1, ZO-1, and occludin)." (PMID 38732594, 2024).
colitis (continued). "However, in the nobiletin-treated DSS group, claudin-1 expression was mainly restricted to the surface epithelium and in a small number of glandular cells and was significantly increased relative to the colitis group." (PMID 39334888, 2024). "In addition, claudin-1 overexpression results in greater susceptibility to and poorer recovery from DSS-induced colitis, making it unclear whether the increase in claudin-1 in our study is a beneficial change or a compensatory mechanism." (PMID 38201850, 2023). "Therefore, we propose that the effects of corylin on AOM/DSS-induced colitis mice are related to the regulation of the colonic mucosal barrier function, where the expression levels of claudin-1, ZO-1, and occludin play important roles in maintaining the intestinal mucosal barrier function." (PMID 35269806, 2022). "Furthermore, we demonstrated that Kae could markedly restore the expression of ZO-1, occludin, and claudin-1 in the murine colitis model, likely recovering the integrity of the intestinal mucosal barrier." (PMID 34367139, 2021). "Hence, we were unable to conclude the role of claudin-1 in the experimental colitis model." (PMID 32630643, 2020). "In addition, TNF-α-induced claudin-1 upregulation leads to ERK and SRC signaling activation, thus contributing to EMT and increased tumor invasion, suggesting the underlying role of claudin-1 in triggering colitis and CAC." (PMID 31316506, 2019). "However, it remains to be determined whether Occludin and Claudin-1 expression change are indeed primarily responsible for daily changes of tight junction permeability and susceptibility to DSS-induced colitis." (PMID 24845399, 2014). "The levels of tight junction proteins (mainly ZO1 and claudin-1) were decreased in DSS-induced colitis mice, whereas the levels of these proteins were elevated in colitis mice with A. shahii As360 treatment." (PMID 39936902, 2025). "The synthesis of essential tight junction proteins, including occludin, claudin-1, and ZO-1, was markedly diminished in DSS-induced colitis, as determined by qPCR examination of colonic tissue." (PMID 40725052, 2025). "In a DSS-induced colitis model, inhibition of HMGB1 was observed to increase intestinal Occludin, E-cadherin, and Claudin-1 expression in experimental mice." (PMID 40689397, 2025). "In the DSS-induced colitis model, HMGB1 overexpression was accompanied by downregulation of the barrier proteins Occludin, E-cadherin, and Claudin-1, which was reversed by DPG intervention, as further corroborated by immunofluorescence staining results." (PMID 40689397, 2025). "Compared to the control group, the expression levels of ZO-1, Claudin-1, and Occludin were markedly decreased in the colon tissues of DSS-induced colitis mice, but QUE treatment significantly enhanced the expression of these TJ proteins." (PMID 39458282, 2024). "SNAI1 has been demonstrated to induce ZEB1 expression and is a potential repressor of E-cadherin and several tight junctions (CLDN1, OCLN, ZO-1) in IECs thereby promoting intestinal barrier dysfunction upon colitis and tumorigenesis in mice." (PMID 37174625, 2023). "Moreover, the RT-PCR analysis further confirmed that the inosine intervention could up-regulate the transcriptional levels of ZO-1, occludin, and claudin-1 in mice with colitis, while a low dose of inosine intervention had little impact on their expression levels." (PMID 37762155, 2023). "In DSS-induced colitis in mice, EMO-NYPs increased the structural integrity of the colon, the number of goblet cells, and zonula occludends-1 (ZO-1), occludin, and claudin-1 expression to promote intestinal mucosa repair." (PMID 37259362, 2023). "Meanwhile, in the pathogenesis of colitis with depletion of epithelial O2, changes in colonic HIF-1α expression are related to barrier permeability through the claudin-1 pathway." (PMID 37509556, 2023).
colitis (continued). "In colitis rats, CGA promotes the assembly of epithelial tight junctions by decreasing the phosphorylation of occludin and claudin-1, thereby reducing intestinal permeability and attenuating intestinal barrier damage." (PMID 37444374, 2023). "The ZO-1, claudin-1 and JAM-1 proteins expressions in intestinal tissues of DSS-induced colitis mice significantly decreased, while occludin protein only showed a decreasing trend." (PMID 35659178, 2022). "Meanwhile, compared with the DSS group, the mRNA expressions of tight junction proteins, including Claudin-1 and occludin were significantly increased in PSPE and PSPc-treated colitis mice (p < 0.05)." (PMID 36358470, 2022). "They increased TNBS-suppressed claudin-1 and mucin barrier protein mucin-2 expression in the colon and claudin-5 in the hippocampus, resulting in the attenuation of TNBS-induced colitis and neuroinflammation." (PMID 35889931, 2022). "After MSC-Exo treatment, the colon length in colitis mice increased; colon inflammatory injury decreased; TNF-α, IL-6, IL-1β, IL-17, and IL-18 levels decreased; and Claudin-1, ZO-1, and IκB levels increased." (PMID 34249964, 2021). "Lactobacillus rhamnosus MTCC-5897 administration before DSS-colitis induction improved intestinal barrier integrity involving transcriptional modulations of TJ genes (ZO-1, OCLN, CLDN-1)." (PMID 34778332, 2021). "In this study, the expression of NLRP3, ASC, and Cleaved caspase-1 was increased while the expression of CLDN1, OCLN, and ZO-1 was decreased in colon tissues of colitis mice, which were reversed by YST to near normal levels." (PMID 34055024, 2021). "Immunofluorescence assay showed that triptolide treatment significantly upregulated the level of claudin-1 and occludin in DSS-induced colitis." (PMID 33240279, 2020). "In a previous study, the expression of claudin-1 and occludin, important indicators of the integrity of the intestinal mucosal barrier, were inhibited in DSS-induced colitis." (PMID 33240279, 2020). "We also investigated the protective effect of PRCC-1301 EVs against DSS-induced disruption of TJs; we examined the expression of TJ proteins including ZO-1, claudin-1, and occludin using immunofluorescence assay in DSS-induced colitis mouse colon tissue." (PMID 33233771, 2020). "We also investigated the effect of sinapic acid on the protein levels of claudin-1, occludin, and ZO-1 in the colon of the DSS-induced colitis mice." (PMID 33312339, 2020). "The in vivo experiment in this study showed that PRCC-1301 EVs recovered the expression and distribution of TJ proteins, ZO-1, claudin-1, and occludin in DSS-induced colitis." (PMID 33233771, 2020). "We observed that the expressions of tight junction proteins, such as claudin-1, occludin, and E-cadherin remarkably reduced in the colonic tissues of DSS induced colitis mice by Western-Blot." (PMID 30708992, 2019). "Consistent with the in vitro experiment, we showed that BS administration recovered expression or distribution of tight junction proteins, ZO-1, Occludin, and Claudin-1, in DSS-induced colitis." (PMID 27912750, 2016). "Our present study also demonstrated that AMD3100 increased the expression of colonic claudin-1, claudin-3, claudon-5, claudin-7 and claudin-8, decreased of colonic claudin-2 expression in DSS-induced colitis." (PMID 22073304, 2011). "The rTsASP2 could directly degrade the TJ proteins Occludin and Claudin-1, thereby increasing paracellular permeability in the intestinal barrier and exacerbating DSS- induced colitis in mice." (PMID 41359687, 2025). "Isobutyric acid pretreatment significantly downregulated pro-inflammatory gene expression (IL-1β, TNF-α, NLRP3, and ASC) while upregulating tight junction components (occludin, claudin-1, and zo-1), demonstrating its protective role against DSS-induced colitis." (PMID 41171006, 2025).
colitis (continued). "The mRNA levels of Occludin, ZO-1 and claudin-1 were also upregulated in the 100 mg/kg of MR2938 group compared with the colitis group, though there was no statistical difference between the two groups." (PMID 41322271, 2025). "Similarly, in this study, the protein levels of tight junction proteins in colon tissue, such as ZO-1, occludin, and claudin-1, were down-regulated in the DSS-induced colitis mice." (PMID 41010526, 2025). "Additionally, sinapic acid exhibited a positive effect on colonic claudin-1, occludin, and ZO-1 in Kunming mice with DSS-induced colitis." (PMID 38732594, 2024). "Furthermore, the oat and oat bran intervention groups were able to increase the expression levels of Claudin-1 and Claudin-5 genes in the colon of DSS-induced colitis mice." (PMID 39770986, 2024). "Immunofluorescence microscopic quantitation and localization demonstrated that the expression of claudin-1 was significantly decreased in the colitis group compared to the non-colitis controls." (PMID 39334888, 2024). "Moreover, we found that BAC treatment led to increases in the expression of junction proteins ZO-1 and Claudin-1, indicating that BAC treatment conferred protection against gut barrier damage in DSS-induced colitis." (PMID 36943054, 2023). "In addition, the gastrointestinal protective effect of DIP has been reported to recover the expression level of claudin-1, occludin, and ZO-1 in the DSS-induced colitis mice." (PMID 34199820, 2021). "FCPS treatment could ameliorate colitis symptoms by restoring the expression of light junction protein claudin-1 and down-regulating the level of TNF-α and IL-1β in the DSS-induced colitis mice." (PMID 34199820, 2021). "Moreover, in IBS-D patients, increased levels of miRNA-29a and miRNA-29b have been described together with a reduction of CLDN1, ZO-1 and nuclear factor-kB repressing factor, while increased levels have also been observed in mice models of IBS or colitis." (PMID 34778332, 2021). "Another research group found that the expression of both OCLN and CLDN3 is reduced and that CLDN1 is not affected in DSS-induced colitis compared to the control group." (PMID 32370215, 2020). "With western blot and immunofluorescence, we found that the protein levels of occludin, claudin-1, and ZO-1 were reduced in DSS-induced colitis colonic tissues, and the reduction in miR-155 levels by miR-155 antagomir treatment increased the expression of these proteins (P<0.01)." (PMID 32713852, 2020). "After EPS-1 administration, the reduced expressions of claudin-1, occludin, and E-canherin proteins were counteracted, which provided another powerful evidence for the protective effects of EPS-1 on mice colitis." (PMID 30708992, 2019). "For example, mice in which differentiation of goblet cells is suppressed, such as those lacking Jak3 or overexpressing Claudin-1, are predisposed to spontaneous and DSS-induced colitis." (PMID 29596476, 2018). "Specifically, the mRNA expression of intestinal barrier proteins (ZO-1, Claudin-1, Occludin and E-cadherin) were elevated, and the activities of antioxidant enzymes (GSH-Px, SOD) in the colon were increased, it exhibited a mitigating influence on the symptoms of colitis in mice." (PMID 41154565, 2025). "Our study showed that the expression of ZO1 and claudin-1 at both mRNA and protein levels and the expression of occludin at mRNA level were significantly reduced in DSS-induced colitis mice, but they were significantly increased in A. shahii As360-treated colitis mice." (PMID 39936902, 2025). "Also in our study, we observed that the GABA-Mo supplementation was able to reduce intestinal inflammation and oxidative stress in DNBS-induced colitis, and was able to partially restore IEB integrity, as evidenced by decreased LBP levels and increased claudin-1 expression." (PMID 39372212, 2024).